TNF (tumor necrosis factor)
Diseases named in the same sentence as TNF in open-access papers (continued):
Sharing a sentence is not in itself a finding about the gene and the disease.
malaria (continued). "In malaria, macrophages release IL-1β and TNF-α after recognizing PAMPs such as glycosylphosphatidylinositol and hemozoin." (PMID 38774541, 2024). "A proportional increase in TGF-β and TNF-a, IL-10, and IL-1β, predicts a proportional increase in severe forms of malaria, especially in CM patients." (PMID 38404582, 2024). "Simultaneously, the IF-γ response has the ability to upregulate TNF-α, indicating that it is a major mediator of malaria pathogenesis." (PMID 39204168, 2024). "These pathways included Bladder cancer, IL-17 signaling pathway, Osteoclast differentiation, Malaria, and TNF signaling pathway." (PMID 39568749, 2024). "On the other hand, concerning the relationship between TNF-α and AA, there were notably significant enrichments observed, specifically in choline binding and infections, including pathways related to Malaria and African trypanosomiasis." (PMID 39063550, 2024). "It was reported that NETs induced by heme and tumor necrosis factor-α (TNF-α) have a key role in malaria immunopathology and severe malaria." (PMID 38286811, 2024). "On the other hand, increased TNF serum levels were repeatedly found in children with severe malaria, establishing the important role that TNF-α plays in malaria pathogenesis." (PMID 37215099, 2023). "TNF-α plays important role in the pathogenesis of multiple inflammatory disorders,autoimmune diseases, and infectious diseases, including malaria." (PMID 38774844, 2023). "Most of the cytokines that were investigated in malaria and other parasite coinfections were TNF, IFN-γ, IL-2, IL-4, IL-6, and IL-10." (PMID 36716305, 2023). "Subsequently, other studies on human malaria showed an association between the severity of anemia and the serum concentration of TNF-α, or that TNF-α was associated with the severe course of the disease." (PMID 36839438, 2023). "Previous studies have shown that strong inflammatory cytokines like TNF-a and IFNg appeared to be blocking Tfh differentiation in malaria-like infections." (PMID 37553348, 2023). "There is evidence showing clinical manifestations of malaria and fatality depends on the host’s immune status, which is mainly orchestrated by inflammatory cytokine tumour necrosis factor-alpha (TNF-α)." (PMID 37910577, 2023). "In contrast, multigravid women had higher percentages of malaria-specific, tumour necrosis factor-alpha (TNFα) -expressing CD4 T cells that correlated with protection from malaria in pregnancy." (PMID 37634385, 2023). "In vitro, SMQ was more lytic to macrophages than LMQ, which limited its ability to induce TNF-α and IL-1β and offered lower protection against malaria." (PMID 37913775, 2023). "TNF levels were increased in malaria coinfections with human African trypanosomiasis and intestinal parasites." (PMID 36716305, 2023). "Meanwhile, TNF levels were significantly decreased in malaria coinfections compared to malaria monoinfection." (PMID 36716305, 2023). "Integrative DNA methylation-mRNA analysis of a top differentially methylated region overlapping the pro-inflammatory gene TNF implicates DNA methylation of TNF cis regulatory elements in the molecular mechanisms of TNF regulation in human malaria." (PMID 37470040, 2023). "During this early phase of malaria, expressions of TNF-α and IL-10 were static in all splenic cells." (PMID 36839438, 2023). "Several VNARs have been reported against different molecular targets, such as VEGF165, TNFα, malaria, and SARS-CoV-2." (PMID 37104207, 2023). "For malaria and virus coinfections, increased TNF, IFN-γ, IL-6, and CCL4 levels and decreased IL-4, IL-7, IL-12, TGF-β, and CCL3 levels were observed in malaria coinfections compared to dengue monoinfection." (PMID 36716305, 2023). "Although IFN- γ can induce the production of TNF-α and other molecules, most studies have demonstrated that malaria and schistosomiasis coinfections have comparable TNF levels compared to malaria monoinfection." (PMID 36716305, 2023).
malaria (continued). "Although TNF had been proposed as a prognostic biomarker of severe malaria, as its levels were increased in patients with severe malaria, this study showed that TNF levels were significantly decreased in malaria and HIV coinfections." (PMID 36716305, 2023). "Another study found that interferon gamma (IFNγ) and tumor necrotic factor alpha (TNF-α) levels are lower in pregnant women who have both malaria and HIV infections." (PMID 36692923, 2023). "TNF-α leads to a significant increase in circulating endothelial EVs in malaria patients varying with disease severity." (PMID 36961624, 2023). "Based on this supposition, patient plasma containing different amounts of IL-10 was selected, and TNF was used as an inflammation readout upon Hz simulation of whole blood from malaria naïve donors." (PMID 37060041, 2023). "Our TNF-focused integrative CpG methylation-TNF mRNA analysis implicates methylation in the molecular mechanisms of TNF regulation in human malaria." (PMID 37470040, 2023). "The notably enriched KEGG pathways were the “interleukin (IL)-17 signaling pathway” (hsa04657), “tumor necrosis factor (TNF) signaling pathway” (hsa04668), “malaria” (hsa05144), and “cytokine-cytokine receptor interaction” (hsa04060)." (PMID 37561311, 2023). "Distinct cytokine profiles in malaria and intestinal parasite coinfections were TNF, IL-2, IL-4, IL-6, and IL-10." (PMID 36716305, 2023). "The choice of cytokines and chemokines measured was based on their reported implication in severe malaria (i.e. IFNγ, TNF-α, IL6, IL-1β, RANTES, MIP-1, MCP-1, IP10)." (PMID 37350957, 2023). "Distinct cytokine profiles in malaria and schistosomiasis coinfections were TNF, IFN-γ, IL-4, IL-5, IL-10, TGF-β, and CXCL8." (PMID 36716305, 2023). "The inflammatory condition of malaria is characterized by free radical generation and excessive release of pro-inflammatory cytokines such as tumor necrosis factor (TNF)-alpha, interleukin (IL)-12, IL-10, IL-6, and interferon (IFN)-gamma." (PMID 36852070, 2023). "Plasma concentrations of TNF-α were shown to be increased in patients with severe malaria and TNF-α levels are discussed to be a potential prognostic biomarker." (PMID 36961624, 2023). "TNF, IFN-γ, IL-6, and IL-12 are proinflammatory cytokines associated with malaria infection and severe malaria." (PMID 36716305, 2023). "While TNF levels were significantly increased in the coinfection group, IL-2 levels were significantly decreased compared to the malaria monoinfection group in two studies." (PMID 36716305, 2023). "TNF and IL-4 levels were significantly decreased in malaria and HIV coinfections compared to malaria monoinfections." (PMID 36716305, 2023). "Distinct cytokine profiles in malaria and human African trypanosomiasis coinfections were TNF, IFN-γ, IL-6, and IL-10." (PMID 36716305, 2023). "Previous meta-analysis indicated that patients with UM had higher TNF-α levels than those with asymptomatic malaria." (PMID 37910577, 2023). "Between them, TNF-α, interleukin 10 (IL-10) and IL-6 are molecules that can be a powerful inflammatory marker of severity during malaria." (PMID 35749690, 2022). "We previously reported HbSS patients infected with Pf had significantly decreased serum levels of IL-8 and the inflammatory ratio of CCL2:TNF compared to malaria infected HbAA patients." (PMID 36618355, 2022). "There were significantly higher odds of TNF-α 308 genotype GA supporting symptomatic malaria compared to asymptomatic malaria in both sites, Obom (p=0.027) and Asutsuare (p=0.027)." (PMID 35291755, 2022). "TNF-α 308 GA resulted in a significant increase in the odds of a person infected with malaria parasites exhibiting symptoms (being symptomatic) in both low and high malaria transmission settings." (PMID 35291755, 2022).
malaria (continued). "As such, polymorphisms in G6PD, MBL2, TNF-α, and NOS2 genes in a group of P. falciparum-infected and P. falciparum-uninfected adults and children living in a low and a high malaria transmission setting in Ghana were characterized." (PMID 35291755, 2022). "It has been reported that, during immunopathogenesis of malaria, IL-6 is regulated by TNF-α and co-operates with other inflammatory mediators to control parasitemia." (PMID 35396564, 2022). "As expected, inflammatory cytokines such as IL-6, IFN-γ, and TNF-α were much higher in severe than in mild malaria patients." (PMID 36293524, 2022). "Numerous studies showed that serum levels of the pro-inflammatory cytokine TNF-α were higher in CM than in severe forms of malaria in children and adults." (PMID 35514965, 2022). "At baseline (C-1), γδ T and CD4+ T cells constituted the majority of cells producing IFNγ or TNF upon PfRBC stimulation among malaria pre-exposed Africans." (PMID 35922467, 2022). "It is worth of noting that despite the decrease in IL-6, this coinfected group showed higher values of TNF-α than malaria." (PMID 35749690, 2022). "Before vaccination, the frequencies of TNFα-secreting T cells in response to malaria antigens were significantly different at baseline between protected and non-protected volunteers." (PMID 35062785, 2022). "An imbalance of cytokines such as tumor necrosis factor (TNF), interleukin-6 (IL-6), IL-10, and interferon-gamma (IFN-γ) are implicated in malaria related-inflammation that induce changes in iron absorption and delocalization." (PMID 36183114, 2022). "Pyrogenic cytokines Interlukin-1 IL1, IL6, and Tumor Necrosis Factor (TNF) are produced in response to malaria parasites." (PMID 35720297, 2022). "Given the importance of the pro-and anti-inflammatory balance during malaria, a comparison was performed between the ratio of the main pro-inflammatory (IL-6 and TNF-α) and anti-inflammatory (IL-10) cytokines identified in the malaria and coinfected groups." (PMID 35749690, 2022). "Particularly, TNFα-secreting CD4+ T cells in response to malaria antigen stimulation, at baseline and after immunization, were associated with protection." (PMID 35062785, 2022). "When it comes to the response to the stimulus and the immune system process of GO terms, combined with KEGG pathways, DEGs were enriched in the pathways in cancer, Legionellosis, Malaria, and the TNF signaling pathway in the LG compared to in the BG." (PMID 35268235, 2022). "As expected, in malaria patients, parasitemia was positively correlated with the anti and pro-inflammatory cytokines IL-10 and TNF-α." (PMID 35749690, 2022). "In the recent meta-analysis, significantly increased TNF-α and decreased IL-12 levels were found in patients with severe malaria compared with patients with uncomplicated malaria." (PMID 36309676, 2022). "TNF-α is an important pro-inflammatory cytokine and during malaria has been correlated with the development of anemia." (PMID 35749690, 2022). "Increased levels of proinflammatory cytokines such as interleukin-1 beta (IL-1β), IL-6, IL-8, IL-10, IL-12, IL-13, IL-31, IL-33, and tumor necrosis factor alpha (TNF-α) have been reported to be related to clinical malaria or severe malaria." (PMID 35396564, 2022). "Previously, researchers discovered that TNF and Th2 group cytokines, such as IL-6 and IL-10 concentrations, were elevated in individuals with severe malaria, indicating that these cytokines play a role in the etiology of malaria disease severity." (PMID 35820892, 2022). "In malaria, TNFα is produced during both the pre-erythrocytic and erythrocytic stages and inhibits parasite growth." (PMID 36415655, 2022). "Production of pro-inflammatory cytokines and chemokines such as IL-1β, IL-6, IL-8, IL-12, IFN-γ, and TNF induce fever and other signs and symptoms in previously unexposed individuals resulting in severe and fatal malaria." (PMID 33746974, 2021).
malaria (continued). "Previous studies demonstrate that high levels of IL-6 as well as TNF-α contribute to complications of malaria such as cerebral malaria." (PMID 34177883, 2021). "The correlation was strongest for IL 10 (r=0.63 p>.0001 and r=0.53, p<.0001 respectively), followed by IL6 (r=0.59, p<.0001) in asymptomatic malaria, and TNF-α in clinical malaria (r=0.48, p<0.001)." (PMID 34177883, 2021). "The ratio between IL-10 levels and parasite density was 0.008 and 0.01 for clinical and asymptomatic malaria respectively, whereas for IL-6 the ratio was 0.0014 versus 0.00088, and for TNF-α 0.0014 versus 0.010." (PMID 34177883, 2021). "Polymorphisms in TNF-α and IL-6 genes, as well higher levels of these markers and of CXCL10 were linked to malaria clinical outcomes and pro-inflammatory activation in response to P. vivax." (PMID 34727121, 2021). "The cytokine profile over eight days of coinfection showed exacerbation in the cytokines MCP-1, IFNγ and TNFα in relation to the increase seen in animals with malaria." (PMID 33526848, 2021). "Inflammatory CD4+ T cells offer protection against malaria by producing IFNγ and TNFα such that P. falciparum infection or its replication is inhibited, thus preventing severe malaria." (PMID 34414129, 2021). "While children with asymptomatic malaria have increased IFNγ, TNF and IL-4 levels, IL-10 and CXCL10 were elevated in asymptomatically infected pregnant women." (PMID 33407502, 2021). "We have found that many of the cytokines involved in malaria (TNF-α, IFN-γ, IL-4, and IL-10) play a double role, as a friend or as an enemy." (PMID 34790829, 2021). "For example, malaria, TNF signaling pathway, and IL-17 signaling pathway were significantly enriched on the NONMMUT001827.2." (PMID 34901457, 2021). "The amount of TNF-α in the plasmas of malaria patients and healthy controls was determined separately by ELISA." (PMID 34359826, 2021). "In the Mali cohort we found that monocytes of adults produced lower levels of the inflammatory cytokines IL-1β, IL-6 and TNF in response to Pf-iRBC stimulation compared to monocytes of infants and children, or malaria-naïve U.S. adults." (PMID 33822828, 2021). "Cytokine concentrations were significantly higher in clinical malaria, whereas the IL-10 and TNF-α over parasite density ratio were higher in asymptomatic malaria." (PMID 34177883, 2021). "On average, significantly less TNF-α is present in the plasmas of malaria patients compared to controls (HAll: 3770 ± 11,925 pg/mL, MAll: 75 ± 160 pg/mL; however, this was not significant (p = 0.0531)." (PMID 34359826, 2021). "The plasma TNF-α cytokine level was significantly increased in most Malaria case in all 3 Malaria groups, with P < 0,05 overall compared to the healthy controls (P = 0,0082, P = <0,0001, P = <0,0001, respectively)." (PMID 34962938, 2021). "We found that monocytes of Malian adults produced lower levels of the inflammatory cytokines IL-1β, IL-6 and TNF in response to Pf-iRBC stimulation compared to monocytes of Malian infants and children or malaria-naïve U.S. adults." (PMID 33822828, 2021). "The markers forming the first cluster tended to increase the MDP values in the group of symptomatic malaria, with remarkable high values of TNF-α, IL-6, CXCL9, AST, CRP, IL-8 and ALT." (PMID 34727121, 2021). "TNF-α and IL-10 levels were increased in Malaria cases versus controls, but IFN-γ and TGF- β levels were comparable between the groups." (PMID 34962938, 2021). "Complicated knowlesi malaria cases often had higher levels of cytokines such as tumor necrosis factor alpha (TNF-α), IL-6, IL-8, IL-1ra, and IL-10." (PMID 34358039, 2021). "Among them, only five studies showed higher TNF-α levels in the cerebral malaria group compared to the severe malaria group." (PMID 32576141, 2020). "A study in India found the EV level to be correlated with TNF-alpha levels and to be significantly elevated in febrile malaria patients." (PMID 32082312, 2020).
malaria (continued). "A positive correlation between IL- 6 and TNF-α was also observed in HIV seropositive pregnant women with malaria coinfection." (PMID 33193759, 2020). "The present study, therefore, seeks to examine the association between cytokines IL- 6, TNF-α, IFN-γ, and some anthropometric indices such as body mass index and blood pressure among pregnant women with HIV-malaria coinfection at NAUTH, Nnewi, Nigeria." (PMID 33193759, 2020). "In this study, it was confirmed that the baseline levels of inflammatory cytokines IL-6, IL-10, IL-12, and TNF-α in malaria-infected donor blood (parasitaemia, 515-1877 parasites/μL of blood) were significantly higher compared to noninfected controls." (PMID 33195706, 2020). "Although all cytokines were elevated in individuals with malaria compared to healthy controls, only IFN-γ and TNF-α were significantly elevated in patients with a first malaria episode compared to individuals with multiple episodes." (PMID 32256470, 2020). "In this study, semi-immune children between 5–15 years old with asymptomatic malaria, had lower Hb levels, increased reticulocyte numbers and erythropoietin levels as well as TNF-α levels, compared to healthy non-malaria carriers, indicating dyserythropoiesis." (PMID 33253198, 2020). "IL-10 also strongly inhibits the production of cytokines such as TNF, IL-I and IL-6, which are involved in malaria pathology." (PMID 32758231, 2020). "In contrast, a separate study showed that monocytes from children with severe malaria had an impaired ability to produce inflammatory cytokines (TNF and IL‐6) to in vitro TLR agonists such as LPS." (PMID 32566226, 2020). "The levels of TNF-alpha were most increased in cerebral malaria than severe malaria groups for adults and children." (PMID 32576141, 2020). "Inflammatory chemokines CXCL10, CCL2, and CCL3 as well as cytokines, TNF-α, IL-8, and IL-6 were differentially expressed in individuals with different hemoglobin genotypes that were infected or uninfected with malaria parasites." (PMID 33424841, 2020). "For children with microscopic asymptomatic malaria, IL-6 was found to positively correlate with TNF-α (r = 0.59, p < 0.0001), IL-4 (r = 0.39, p = 0.017), and IL-10 (r = 0.50, p = 0.002)." (PMID 33281757, 2020). "The plasma concentrations of TNF-alpha are increased in patients with malaria, which results in a significant elevation of circulating endothelial EVs in malaria patients with different degrees of disease severity." (PMID 32082312, 2020). "The only exception was for TNF-α/IL-4 which was significantly increased in children with microscopic asymptomatic malaria compared to uninfected controls using the Mann-Whitney test (p = 0.044)." (PMID 33281757, 2020). "In some cases, a surge in inflammation due to malaria infection leads to severe or moderate malaria, specifically due to higher levels of circulatory pro‐inflammatory cytokines, such as TNF and IL‐6, but IL-10 regulates the outcome." (PMID 32033605, 2020). "Malaria PbA infection increased lipid peroxidation, and the release of TNF and-α IFN-Υ, and capsazepine (antagonist of transient receptor potential channels, of the vanilloid subtype—TRPV1)-treated group had lower levels of these products." (PMID 32599864, 2020). "We show that individuals with microscopic asymptomatic malaria had significantly increased levels of TNF-α and IL-6 compared to uninfected controls." (PMID 33281757, 2020). "Another study in India has recently shown that women with Pv malaria in pregnancy have more IL-6, TNF and IL-1β in peripheral plasma than uninfected pregnant women." (PMID 32365058, 2020). "In accord with our observations, decreased TNF-α in children with malaria and bacteremia relative to children with malaria alone has been observed previously." (PMID 32958528, 2020). "Higher plasmaconcentrations of TNF-α were reported in severe malaria cases compared to uncomplicated malaria in Sri Lanka." (PMID 33424841, 2020).